SOX9 (SRY-box transcription factor 9)
Diseases named in the same sentence as SOX9 in open-access papers (continued):
Sharing a sentence is not in itself a finding about the gene and the disease.
sarcoma (3 papers, 2020 to 2024). A usually aggressive malignant neoplasm of the soft tissue or bone. "Then, we analyzed the expression of biomarkers of osteoblasts (COL1A1, BGLAP and RUNX2), chondrocytes (COL2A1, COMP and SOX9) and sarcoma (POSTN and DCN), adipocyte (LPL and PPARG) and BMSCs." (PMID 39715773, 2024). "In uterine sarcoma, upregulation of SOX9 promotes epithelial-mesenchymal transition, leading to sarcoma formation." (PMID 36003340, 2022). "Almost all analyzed chondroid areas of the sarcoma samples were strongly positive for SOX9 (17/19), whereas in the dedifferentiated high-grade parts only three out of 29 samples revealed SOX9 reactivity in single cells." (PMID 33076370, 2020). "Thereby, a clear difference was observed between SOX9 reactivity in low-grade (highly differentiated and still cartilaginous) and high-grade, dedifferentiated (non-cartilaginous) parts of the sarcoma samples." (PMID 33076370, 2020). "We showed via TMA that SOX9 is almost exclusively and highly expressed in the low-grade, cartilaginous compartment of DDCS, but not in the dedifferentiated parts, and might thereby be useful as a marker to distinguish between the two different areas within the sarcoma." (PMID 33076370, 2020).
testicular cancer (3 papers, 2013 to 2023). A primary or metastatic malignant neoplasm that affects the testis. "In a testicular cancer cell line, phosphorylation of SOX9 promoted its nuclear translocation." (PMID 37229206, 2023). "However, we observed that knockdown of PTGDS or SOX9 expression effectively alleviated both RIG1 and H-rev107-mediated inhibition of cell migration and invasion in testis cancer cells." (PMID 23687991, 2013). "The facts that the increase in PGD2 production and SOX9 expression through PTGDS activation in H-rev107 and RIG1 transfected NT2/D1 cells shown in this and our previous studies support pro-differentiation activities of both RIG1 and H-rev107 in testis cancer cells." (PMID 23687991, 2013).
testicular disorder (3 papers, 2014 to 2024). A non-neoplastic or neoplastic disorder affecting the testis. "It has been suggested that changes in SOX9 expression resulting from disruptions in some regions upstream of SOX9 could be important in 46,XX testicular disorder of sexual development." (PMID 25529318, 2014).
thymoma (3 papers, 2021 to 2023). A neoplasm arising from the epithelial cells of the thymus. "In this study, we observed that SOX9 expression was associated with the tumor microenvironment (TME) of thymoma, with SOX9 expression positively correlated with the tumor stromal scores while negatively with the tumor immune scores." (PMID 34778027, 2021). "SOX9 expression was significantly associated with histological type and high expression indicated unfavorable clinical outcomes of thymomas." (PMID 34778027, 2021). "In conclusion, the authors suggest that SOX9 expression might be associated with an immune suppressive microenvironment of thymomas." (PMID 36551568, 2022). "Moreover, high SOX9 expression was associated with immune dysregulation of thymoma, and M2 macrophage significantly dominated in the high SOX9 expression group." (PMID 34778027, 2021). "Taken together, our results indicated that SOX9 expression might be associated with the tuft cell phenotype of thymoma." (PMID 34778027, 2021). "Taken together, we proposed that SOX9 expression might be associated with an immune suppression tumor microenvironment of thymomas." (PMID 34778027, 2021). "We analyzed the association of SOX9 expression with clinical parameters of thymoma patients, including age, sex, and histological type, and found that SOX9 expression tended to correlate with the histological type of thymomas (P = 0.0131)." (PMID 34778027, 2021). "Correlation between SOX9 RNA expression and clinicopathological parameters of patients with thymomas in the TCGA cohort." (PMID 34778027, 2021). "High SOX9 expression was observed in 14 of 15 (93%) cases with type A, 24 of 36 (67%) cases with type AB, and 8 of 14 (57%) cases with type B3 thymomas." (PMID 34778027, 2021). "In thymomas, we found that SOX9 expression was positively correlated with the expression of HIPK2, which is a critical transcriptional factor determining thymic tuft cells development and shaping thymic function." (PMID 34778027, 2021). "Correlation between SOX9 protein expression level and clinicopathological parameters of patients with thymomas in our cohort." (PMID 34778027, 2021). "Taken together, these data further supported the notion that SOX9 might be used as a marker for thymic epithelial cells and explained the association of its expression with the histological type of TETs, especially the one representing a tuft cell phenotype of thymomas." (PMID 34778027, 2021). "To further explore the potential function of SOX9 in thymoma, we first performed gene set enrichment analysis (GSEA)." (PMID 34778027, 2021). "To further verify the clinical significance of SOX9 expression in TETs, we examined SOX9 expression using the RNA-seq data of thymomas in TCGA." (PMID 34778027, 2021). "Then, SOX9 expression in thymomas was categorized into high and low expression groups, with the median level of SOX9 expression selected as the cutoff." (PMID 34778027, 2021). "Specifically, strong staining of SOX9 was observed in 6 of 8 (70%) cases with type A, 3 of 6 (50.00) of cases with type AB, 2 of 9 (22.22%) cases with type B2 thymomas, and 9 of 20 (45%) cases with thymic carcinomas." (PMID 34778027, 2021). "The authors advocate that SOX9 expression is correlated with the histological type of thymomas, and, consequently, it could be a dismal prognostic marker for thymomas." (PMID 36551568, 2022). "Additionally, high expression of SOX9 was observed in 70% of type A, 50% of type AB, 22.22% of type B2 thymomas, and 45% of thymic carcinomas cases." (PMID 36551568, 2022). "Together, these results indicated that SOX9 expression was associated with the epithelial phenotype instead of immune phenotype of thymomas, and we proposed that SOX9 might be used as a potential marker for the epithelial components of thymomas." (PMID 34778027, 2021).
thymoma (continued). "Further bioinformatics analysis of gene expression profiles of thymomas with high and low SOX9 expressions and the corresponding survival analyses were based on the thymoma cases identified in The Cancer Genome Atlas (TCGA) database, with the median expression level of SOX9 selected as cutoff." (PMID 34778027, 2021). "In addition, we found that thymoma patients with higher SOX9 expression had less infiltration of B cells, CD4+ T cells, and CD8+ T cells, but higher infiltration of macrophages." (PMID 34778027, 2021). "Moreover, SOX9 was largely expressed in the nuclei of TET tumor cells, and, according to the authors, it could be a diagnostic marker for thymomas." (PMID 36551568, 2022). "Notably, SOX9 expression in TETs might indicate a tuft cell phenotype and an immune suppressive microenvironment of thymomas." (PMID 34778027, 2021). "Notably, high SOX9 expression in TETs may indicate a tuft cell phenotype and an immune suppressive microenvironment of thymomas." (PMID 34778027, 2021). "Moreover, SOX9 was observed to be highly expressed in the nuclei of TET tumor cells and may serve as a diagnostic marker for thymomas." (PMID 34778027, 2021). "In addition, SOX9 expression was positively associated with POU2F3 and TRPM5 expressions, the master regulators of tuft cells, suggesting that high SOX9 expression might be associated with the tuft cell phenotype of thymomas." (PMID 34778027, 2021). "Together, these findings suggested that SOX9 expression might indicate a competitive interaction between M2 macrophages and CD8+ T cells, and an immune suppressive microenvironment of thymomas, which consequently led to enhanced pro-tumorigenic activity." (PMID 34778027, 2021). "Of note, SOX9 expression was significantly correlated with the histological type of thymomas and might serve as a negative prognostic marker for thymomas." (PMID 34778027, 2021).
Tracheomalacia (3 papers, 2011 to 2025). "Genetic deletion of Wls, which encodes the cargo protein essential for Wnt ligand secretion from the tracheal epithelium, leads to a loss of Sox9 expression in the tracheal mesenchyme and a failure in chondrocyte development, causing eventual tracheomalacia." (PMID 33328171, 2020). "Disruption in HH signaling can similarly result in tracheomalacia and loss of Sox9+ tracheal chondrocytes in mice." (PMID 33328171, 2020). "In this study, we show that conditional mouse mutants with relatively high levels of GliR, mimicking PHS, exhibit tracheomalacia and fail to properly specify Sox9+ tracheal chondrocytes." (PMID 33328171, 2020). "Both the Smof/f mutants, which mimic an absence of GliA function, and Gli3TFlag/+ mutants, which have excess Gli3R, exhibit tracheomalacia and a reduction of Sox9." (PMID 33328171, 2020). "Altogether, our data provide a mechanistic understanding of how disruptions in HH/Gli signaling may impair specification of Sox9+ tracheal chondrocytes and ultimately lead to tracheomalacia." (PMID 33328171, 2020). "Here, we use conditional Smof/f mouse mutants, which lack GliA, and Gli3TFlag/+ transgenic mice, which overexpress Gli3R, to show that imbalance of Gli activator and repressor activity disrupts specification of Sox9+ tracheal chondrocytes, resulting in a tracheomalacia phenotype." (PMID 33328171, 2020). "Interestingly, after heterozygous Sox9 deletion besides camptomelia also hip displacement, hypoplasia of the patella, and tracheomalacia was reported." (PMID 21826198, 2011).
viral infection (3 papers, 2012 to 2023). "While there was a significant amount of Pax3 and Pax7 protein expression at the beginning of culturing, Pax3 and Pax7 became gradually diminished upon Nkx3.2 and Sox9 viral infection, concurrently with the induction of cartilage genes, which should be consistent with a transdifferentiation process." (PMID 22768305, 2012). "We detected viral infection in both SOX2+ airway and SOX9+ alveolar cells." (PMID 37084725, 2023).
Waardenburg syndrome (3 papers, 2020 to 2022). A disorder characterized by varying degrees of deafness and minor defects in structures arising from neural crest, including pigmentation anomalies of eyes, hair, and skin. "Six new genes were associated with NSHI: INPP4B, CCDC141, MYO19, DNAH11, SOX9, and POTEI; and one new gene, PAX8, was associated with Waardenburg syndrome." (PMID 35440622, 2022).
acute pancreatitis (2 papers, 2015 to 2021). An acute inflammatory process that leads to necrosis of the pancreatic parenchyma. "Based on the observed induction of Mecom after 48 h of caerulein-induced acute pancreatitis, we investigated Mecom expression in Sox9 loss-of-function mice under similar conditions." (PMID 33762742, 2021). "In addition, our preliminary experimental results showed the emergence of Sox9/Ptf1a double positive cells in the tissue restoration after cerulein-induced acute pancreatitis." (PMID 25687338, 2015).
adult brain tumor (2 papers, 2015 to 2016). "In contrast, SOX9 may serve as oncogene in lung, skin, prostate and brain cancers." (PMID 26036262, 2015).
age-related macular degeneration (2 papers, 2022 to 2024). Age-related loss of vision in the central portion of the retina (macula), secondary to retinal degeneration. "SOX9 ChIP-Seq analysis in differentiated hES-RPE revealed that several SOX9 target genes are involved in the early stages of age-related macular degeneration (AMD)." (PMID 36114905, 2022).
amyotrophic lateral sclerosis (2 papers, 2018 to 2021). Amyotrophic lateral sclerosis (ALS) is a neurodegenerative disease characterized by progressive muscular paralysis reflecting degeneration of motor neurons in the primary motor cortex, corticospinal tracts, brainstem and spinal cord. "SRY-box transcription factor 9 (SOX9) is found to be almost exclusively expressed by astrocytes in the adult human CNS, and its strong upregulation was reported in a rodent amyotrophic lateral sclerosis model." (PMID 34572572, 2021).
aneurysm (2 papers, 2021 to 2023). Bulging or ballooning in an area of an artery secondary to arterial wall weakening. "Augmented Sox9 and reduced Opn gene expression are associated with aneurysm development, calcification and hyperchondroplasia." (PMID 34829747, 2021). "The present investigation demonstrates that Light genetic deficiency aggravates aneurysm development by promoting VSMC switching to detrimental phenotypes associated with SOX9 expression." (PMID 34829747, 2021). "Augmented mRNA levels of the Sox9 gene and diminished Opn gene expression, which are both associated with vascular lesion development and osteochondrogenesis, were also observed in Light-deficient aneurysm tissue." (PMID 34829747, 2021). "The increased expression of the Sox9 marker in Light-deficient aneurysms, which has been shown to aggravate vascular lesions and to be determinant in VSMC osteochondrogenic phenotype, points to a protective role of LIGHT against VSMC trans-differentiation toward detrimental phenotypes." (PMID 34829747, 2021). "For future studies, it is important to define the role of increased SOX9 expression in aneurysm development following YAP/TAZ deletion, and to target specific immune responses to reduce vascular inflammation in this model." (PMID 37561588, 2023).
aortic valve stenosis (2 papers, 2024 to 2025). Aortic valve stenosis (AVS) is a condition characterized by narrowing of the heart's aortic valve opening. "Overdoses of vitamin A result in retinoic acid receptor/retinoid X receptor-dependent suppression of Sox9, leading to aortic valve stenosis and leaflet calcification." (PMID 41325840, 2025). "Furthermore, in vivo, SOX9 knockdown ameliorated granulation proliferation and tracheal fibrosis, as manifested by reduced tracheal stenosis." (PMID 38993791, 2024).
asthma (2 papers, 2014 to 2025). "In asthma, if VEGF‐A levels are decreased, the transcription factor Sox9 is upregulated, driving the club to goblet cell differentiation, exacerbating disease." (PMID 39502000, 2025).
bile duct adenoma (2 papers, 2021). A benign, well-demarcated polypoid neoplasm arising from the bile duct epithelium. "Morphological analysis of the tumors developed in the 11–13 months old Sox9-Pten livers revealed that the tumors developed are heterogeneous, consisting of both HCC (50%, 11 out of 22) and CCA/bile duct adenoma (BDA) (63.6%, 14 out of 22)." (PMID 34083580, 2021).
cardiomyopathies (2 papers, 2021 to 2024). "Considering that SOX9 upregulates FOXK2 expression by directly binding to the FOXK2 promoter, it is speculated that FOXK2 may play a role in SOX9-mediated cardiac fibrosis or other cardiomyopathies." (PMID 38741782, 2024).
Cholestatic liver disease (2 papers, 2018 to 2023). "GCA treatment of hepatocytes from AlbCre+ Rbpj+/+ and AlbCre+ Rbpj−/− mice mimics a cholestatic liver disease in both genotypes and results in an increase of Sox9 mRNA level." (PMID 30501048, 2018). "For instance, transforming growth factor β85 signal and Transcription factor SOX-9 (SOX9) can promote the formation of the biliary system in hepatocytes and potentially alleviate cholestatic liver disease." (PMID 37324459, 2023).
chondroblastoma (2 papers, 2018 to 2024). A benign, chondroid-producing, well-circumscribed, lytic neoplasm usually arising from the epiphysis of long bones. "An analysis of 206 specimens of bone tumours showed that among the indicators with diagnostic utility, including SP7, IHH, RUNX2, SOX9 and TWIST1, only RUNX2, TWIST1 and SOX9 are sensitive and specific factors that differentiate between chondroblastoma and chondromyxoid fibroma." (PMID 29899399, 2018). "In the chondroblastoma, H3K36M showed diffuse nuclear expression in almost all cases, and DOG1 and SOX9, although not specific, may be focally positive." (PMID 39850815, 2024).
chondroma (2 papers, 2015 to 2022). A benign well circumscribed neoplasm of hyaline cartilage arising from bone or soft tissue. "On histopathological examination, the tumor was diagnosed as chondroma; Vimentin, Ki-67 (6%), SOX-9, and S-100 stained positive, but CK, CK18, EMA, CD34 and GFAP stained negative." (PMID 35692788, 2022). "On histopathological examination, the tumor was diagnosed as chondroma; Vimentin, S-100 and Ki-67(2%) stained positive, but EMA, CK, CK18, CD34, SOX-9 and GFAP stained negative by ICH." (PMID 35692788, 2022).
cleft lip (2 papers, 2013 to 2022). Congenital defect in the upper lip where the maxillary prominence fails to merge with the merged medial nasal prominences. "The general aim of the study was to identify the role of SOX9 in the aetiology of Pierre Robin syndrome associated with cleft lip / palate, which is a common and complex congenital malformation caused by environmental and genetic factors." (PMID 23826492, 2013). "This led us to consider SOX9 as the primary candidate gene in patients with cleft lip/ palate associated with Pierre Robin syndrome." (PMID 23826492, 2013).
clubfoot (2 papers, 2020 to 2025). The most common congenital deformation of the foot, occurring in 1 of 1,000 live births. "They explain the bowed bones, loss of a pair of ribs, and clubfoot observed in CD patients, who had insufficient SOX9 dosage to support the skeletal development due to a loss-of-function mutation in a SOX9 allele." (PMID 40025280, 2025).
co-infection (2 papers, 2012 to 2019). "This is further confirmed by our RT-PCR analysis that showed diminished expression of collagen II mRNA as well as aggrecan mRNA upon Nkx3.2ΔC-VP16 and Sox9 co-infection." (PMID 22768305, 2012). "We found that total GAG content in the satellite cells was significantly induced by Sox9 as well as Nkx3.2/Sox9 co-infection, which is consistent with the qRT-PCR analysis for aggrecan." (PMID 22768305, 2012). "Similarly, BMP9-induced expression of chondrogenic regulator Sox9 and adipogenic regulator Pparγ was also effectively diminished by AdR-simRmst co-infection, suggesting that Rmst may be an important mediator of BMP9-induced multiple-lineage differentiation of MSCs." (PMID 31825894, 2019). "Strikingly, we found that while Sox9-treated satellite cells dramatically upregulated collagen II expression, Nkx3.2ΔC-VP16 co-infection with Sox9 led to a dramatic reduction in this cartilage matrix protein." (PMID 22768305, 2012).
colitis (2 papers, 2024 to 2026). Inflammation of the colon. "Our data demonstrated that mucosal regeneration is closely correlated with the number of LGR5-expressed epithelial cells with a positive correlation of Lgr5 and Sox9, following the chronic phase of DSS-mediated colitis." (PMID 41596428, 2026).
COVID-19 (2 papers, 2021 to 2025). A disease caused by infection with severe acute respiratory syndrome coronavirus 2. "ACE2 expression in multiple types of lung cells including SOX9 positive progenitor cells, in cooperation with an unestablished immune system, could be risk factors contributing to vulnerability of infants with COVID-19." (PMID 33500718, 2021).
Crohn disease (2 papers, 2016 to 2024). A gastrointestinal disorder characterized by chronic inflammation involving all layers of the intestinal wall, noncaseating granulomas affecting the intestinal wall and regional lymph nodes, and transmural fibrosis. "A team of scientists studying the mechanisms for increased transcription factor SOX-9 (SOX-9) expression in Crohn’s disease found a decrease in miR-145 levels due to a hypermethylated promoter site." (PMID 38958690, 2024). "A different report shows an opposite correlation between SOX9 and CEACAM1 in Crohn's disease." (PMID 26885752, 2016).
cutaneous melanoma (2 papers, 2019 to 2021). A primary melanoma arising from atypical melanocytes in the skin. "Many REs of CNCC regulators, such as SOX9/10, were also inactive in Skin Cutaneous Melanoma." (PMID 33824393, 2021).